CCL2 (C-C motif chemokine ligand 2)
Diseases named in the same sentence as CCL2 in open-access papers (continued):
Sharing a sentence is not in itself a finding about the gene and the disease.
myocarditis (31 papers, 2009 to 2025). Myocarditis is a condition that is characterized by inflammation of the heart muscle (myocardium). "Nuclear factor kappa-light-chain-enhancer ofactivated B (NF-κB) is a key inflammation-related transcription factor.In myocarditis, the activation of NF-κB is closely related to theupregulation of chemokines, including CCL2, CCL3, and CXCL2." (PMID 40927089, 2025). "Quantitative RT–PCR analysis of sorted cardiac fibroblasts confirmed the increased expression of the inflammatory monocyte-attracting chemokine Ccl2 and the inflammatory cytokine Il6 during autoimmune T cell-driven myocarditis." (PMID 39196111, 2024). "This was demonstrated by significantly higher serum CCL2 levels in patients with acute myocarditis on admission than in healthy volunteers and significantly higher serum CCL2 levels in patients who died of acute myocarditis than in surviving patients." (PMID 36110847, 2022). "Regulation the inflammatory infiltration of EAM by adjusting CCL2 expression through Act1/TRAF6/TAK1 is one of the pathological mechanisms of myocarditis." (PMID 36110847, 2022). "In clinical studies, elevated CCL2 levels at first occurrence in patients with acute myocarditis were dramatically related to severity of disease and prognosis." (PMID 36110847, 2022). "In vivo blockade of CCL2 activity reduced the severity of CVB3-induced myocarditis, and the main mechanism may be related to effective inhibition of chemotaxis and reduction of systemic and local Th1 immune responses." (PMID 36110847, 2022). "In the present study, we found high levels of CCL2 among mice single-infected with CL Brener, which can explain, at least in part, the intense myocarditis characterized by inflammatory infiltrate (predominantly constituted of mononuclear cells) observed among these animals." (PMID 20967289, 2010). "Moreover, the serum CCL2 level was even higher in patients who diedfrom acute myocarditis." (PMID 40927089, 2025). "This peptide inhibits the inflammatory chemokines CCL2, CCL3, CCL7, and CCL8 in murine Coxsackievirus B3 (CVB3) infection, a viral trigger of myocarditis." (PMID 40009121, 2025). "Cardiac tissue biopsy samples from patients with myocarditis were enriched for CCR2+ cells and had elevated CCL2 and CCR2 mRNA expression compared to control specimens obtained from individuals dying from trauma with no history of cardiac disease." (PMID 36110847, 2022).
lymphopenia (30 papers, 2017 to 2025). Reduction in the number of lymphocytes. "Moreover, up-regulation of proapoptotic proteins (B-cell lymphoma-2 protein-BCL-2, C-X-C motif chemokine ligand 10- CXCL10, and C-C motif chemokine ligand 2- CCL2) as well as interleukin 6 (IL-6) were presented as molecular alterations associated with lymphopenia in patients with this infection." (PMID 37046564, 2023). "Hematopoietic alterations are characterized by lymphopenia, thrombocytopenia, thromboembolism, and increased plasma levels of inflammatory cytokines and chemokines (i.e., IL-6, CCL2, TNF-α)." (PMID 34944747, 2021). "From the little we know in the inflammatory response triggered by SARS-CoV-2, during this infection lymphopenia is observed, with loss of CD4 + and CD8 + T cells, hyperproduction of IL6, IL10, IL2R, TNFa and CCL2." (PMID 32883368, 2020). "The release of chemokines such as CXCL-10/IP-10 and CCL-2/MCP-1 may also contribute to CD4 lymphopenia, mostly due to the suppression of hematopoietic progenitor cells proliferation, or to the inhibition of IL-2 signaling pathway." (PMID 34122423, 2021). "Additionally, CXCL10 and CCL2 were highly expressed in patients with SASR-CoV infection, especially their upregulation expressions can inhibit the development of hematopoietic precursor cells and cause lymphopenia in patients infected with SASR-CoV." (PMID 37087411, 2023). "In contrast, chemokines such as CCL2 and IP-10 have been shown to suppress the growth of hematopoietic stem cells in SARS-CoV infection resulting in frequently observed lymphopenia in the disorder." (PMID 37376437, 2023). "On the other hand, lymphopenia observed in the infected hamsters strongly correlated with the increased levels of IL-1β, IFN-γ, CXCL10, and CCL2, indicating a dysregulation of T-helper-1 (Th1) cell function." (PMID 36618412, 2022). "Parallels seen in late-stage disease mice include: high viral loads (RNAemia), elevated AST and ALT, elevated neutrophils, lymphopenia, and increases in IL-10, IL-6, IFN-γ, CCL2, CCL5, and TNF-α." (PMID 31790513, 2019). "CXCL-10/IP-10 and CCL-2/MCP-1 could suppress haematopoietic progenitor cells proliferation, ultimately leading to lymphopenia." (PMID 32922406, 2020).
acute coronary syndrome (27 papers, 2007 to 2025). Signs and symptoms related to acute ischemia of the myocardium secondary to coronary artery disease. "Monocyte chemoattractant protein 1 (also called CCL2) plays an important role in the pathogenesis of acute coronary syndrome." (PMID 23880849, 2013). "Moreover, the enhancement of CCL2 secretion from neutrophils may contribute to the higher plasma CCL2 level in subjects with acute coronary syndromes." (PMID 33715310, 2021).
anemia (27 papers, 2013 to 2025). A reduction in the number of red blood cells, the amount of hemoglobin, and/or the volume of packed red blood cells. "On the other hand, the circulating levels of IL-1β, IL-8, CXCL10, IL-6, CCL4, IL-1RA and CCL2 displayed an inverse behavior, with rising levels being proportional to increases in anemia severity." (PMID 37143662, 2023). "Higher CCL2 levels correlated with transfusion dependency, marked splenomegaly, and significantly lower anemia response to IMIDs, clearly indicating a more aggressive disease." (PMID 37760903, 2023). "IL-2, sIL-2R, IL-6, IL-8, IL-12, IL-17, MCP-1/CCL2, and MIP-1α correlate with anemia/RBC transfusion dependency while IL-6, IP-10/CXCL-10 and MIP-1β correlate with thrombocytopenia." (PMID 37760903, 2023). "Nampt/PBEF/visfatin expression in nontumor tissue, both mRNA and protein, increased in patients with metastatic disease and mild anemia, and, on transcriptional level, correlated with HIF1α, IL1β, IL8, CCL2, and CCL4 expression." (PMID 26075243, 2015).
gout (27 papers, 2010 to 2025). A condition characterized by painful swelling of the joints, which is caused by deposition of urate crystals. "Previous studies have demonstrated that the CCL2 −2518A/G (rs1024611) single nucleotide polymorphism (SNP) plays a key role in the susceptibility to gout in Chinese Han male populations." (PMID 41311848, 2025). "A functional SNP in CCL2 gene promoter region, rs1024611 (-2518A/G) was associated with gout in a study of a Chinese male cohort." (PMID 30123371, 2018). "Chemokines such as MMP-9 and CCL-2 contribute to the inflammation associated with gouty arthritis." (PMID 36297105, 2022). "By secreting CCL2, activated resident synoviocytes may display the ability to recruit monocytes into the joints and, in turn, to set in the inflammatory response that underlies the acute attack of gout." (PMID 20149224, 2010). "Studies on the contribution of chemokine CCL2 in the progression of gout have revealed a positive correlation between low methylation in the promoter region and enhanced inflammatory responses in gout among Chinese Han men." (PMID 41311848, 2025). "On the other hand, a latest research in patients with gout and asymptomatic hyperuricemia shows us that hyperuricemia leads to elevated serum CCL2 and monocyte recruitment." (PMID 24772444, 2014). "In vivo studies suggest that CCL2 attracts monocytes to sites of inflammation in a variety of pathologic conditions, including atherosclerosis, pulmonary fibrosis and granulomatous lung disease, and degenerative and inflammatory arthropathies, including gout." (PMID 20149224, 2010). "The premise that CCL2 is immediately available in joints subjected to attacks of inflammatory agents suggests that in gout, monocytes may precede neutrophil infiltration." (PMID 20149224, 2010). "Elevated levels of CCL2 were measured in synovial fluid of gout patients." (PMID 20149224, 2010). "Indeed, previous study have shown that elevated CCL2 levels in the serum are correlated with increased amounts of circulating CD14+ monocytes in subjects with gout and asymptomatic hyperuricemia, suggesting the possible role of CCL2 in the priming and trafficking of monocytes in gout." (PMID 29056937, 2017). "Compared with WT mice, St2-/- mice showed significantly reduced expression of IL-1β, IL-6, IL-13, CCL11, G-CSF, CXCL1, CCL2 and CCL3 proteins in ankle tissues, suggesting St2-/- mice showed generally attenuated inflammatory response during gout." (PMID 33204337, 2020). "In contrast to differential miR-339-5p, miR-486-5p, and miR-361-5p expression pattern, the roles of CCL2 and CXCL8 in gout patients are well known." (PMID 30854012, 2019). "There are no publications on the involvement of these miRNAs in gouty arthritis or correlations with CCL2 and CXCL8." (PMID 30854012, 2019). "Further, blocking of C5a but not of CCL2 significantly decreased the monocyte migration in response to joint fluids from gout patients." (PMID 29056937, 2017). "Besides, in gouty arthritis models, intraarticular injection of MSU crystals induces the rapid release of CCL2 within 1 hour after injection, reaching a maximum at 2 to 4 hours." (PMID 20149224, 2010).
IgA nephropathy (27 papers, 2013 to 2025). "Genetic variants of CCL2 are also correlated with the IgA nephropathy risk in humans." (PMID 33159802, 2021). "Urinary exosomal excretion and CCL2 mRNA level were increased in IgA nephropathy and correlated with the disease activity." (PMID 32082158, 2019). "Urinary exosomal excretion and chemokine (C-C motif) ligand-2 (CCL2) mRNA level were increased in IgA nephropathy and correlated with the disease activity." (PMID 32082158, 2019). "Moreover, exosomal CCL2 mRNA is a biomarker of active histological injury in IgA nephropathy." (PMID 36915206, 2023). "The C-C motif chemokine ligand 2 (CCL2)/CCR2 signaling axis is traditionally recognized as a principal mechanism for monocyte recruitment, particularly in DKD, IgA nephropathy (IgAN), and ischemia–reperfusion injury (IRI)." (PMID 41050663, 2025).
glomerular diseases (26 papers, 2012 to 2025). "For instance, as recently reviewed, the chemokines CCL2, CCL3, and CCL4 correlate with the severity of S. mansoni, where CCL3 is related to the recruitment of eosinophils and induction of granulomatous pathology, while CCL2 is associated with glomerulopathy." (PMID 26082781, 2015). "Many studies have associated CCL2/MCP-1 with glomerulopathies and with renal transplantation." (PMID 24692841, 2014). "CCL2, also known as macrophage chemokine-1 (MCP-1), is involved in the development of glomerular diseases by facilitating the recruitment of macrophages via interaction with type 2 C-C chemokine receptor (CCR2)." (PMID 40103820, 2025). "During glomerular disease, Twist1 in podocytes limited CCL2-induced recruitment of monocytes/macrophages into the glomerulus and thereby mitigated damage driven by TNF-α–elaborating proinflammatory macrophages." (PMID 34369383, 2021). "Our current studies demonstrate that Twist1-regulated CCL2 generation played a pivotal role in crosstalk between podocytes and macrophages during the development of podocyte injury and glomerulopathy." (PMID 34369383, 2021). "The glomerular expression levels of CCL2 and its receptor CCR2 were found to be elevated in human glomerulopathies, and CCL2/CCR2 signaling may mediate the development of a variety of glomerular diseases." (PMID 40103820, 2025).
hyperlipidemia (26 papers, 2010 to 2025). "Hub genes Adipoq and Ccl2 are thought to play essential roles in PM2.5-related hyperlipidemia." (PMID 37888673, 2023). "During atherogenesis, primarily classical monocytes adhere to the endothelium to contribute to lesion development, likely due to their increased mobilization into the circulation during hyperlipidemia, which is mediated by the CCL2/CCR2 axis (already under steady state) and by the CXCL1/CXCR2 axis." (PMID 26001902, 2015).
lung adenocarcinoma (26 papers, 2005 to 2026). A carcinoma that arises from the lung and is characterized by the presence of malignant glandular epithelial cells. "Peritumoral AMs, which promote tumor growth by secreting IL‐10 and CCL2, have been implicated in poor prognosis in patients with lung metastases of non‐pulmonary origin and those with primary lung adenocarcinoma." (PMID 40051246, 2025). "Hypoxia‐associated stabilization of HIF‐1A markedly enhanced miR‐210‐3p expression, which directly targets CCL2 downregulation in lung adenocarcinoma, resulting in impaired monocyte infiltration and the stimulation of macrophage TAM polarization." (PMID 35658112, 2024). "The lower level of CCL2 was also evident in the tissue lysates, pleural fluid, and serum sample of lung adenocarcinoma patients." (PMID 35658112, 2024). "All these results demonstrate the role of miR‐210‐3p in the downregulation of CCL2 expression in the hypoxic lung adenocarcinoma cells, which restricts monocyte migration and its TAM polarization in the hypoxic tumor microenvironment." (PMID 35658112, 2024). "A negative correlation between mir‐210‐3p expression and CCL2 levels in human lung adenocarcinoma patients incites further investigation of the role of miR210‐3p in CCL2 regulation in hypoxic tumors." (PMID 35658112, 2024). "Our study has revealed the role of HIF‐1A on CCL2 expression when examining the HIF‐1A silenced or overexpressed lung adenocarcinoma cell lines." (PMID 35658112, 2024). "HIF‐1Α stabilization increases miR‐210‐3p levels in lung adenocarcinoma and impairs monocyte infiltration by inhibiting CCL2 expression." (PMID 35658112, 2024). "Mechanistic studies were performed on lung adenocarcinoma cell lines and 3D tumor spheroids to understand the role of hypoxia‐induced miR‐210‐3p in the regulation of CCL2 expression and macrophage polarization." (PMID 35658112, 2024). "We began our tumor studies by assessing the expression of CCR2 and MCP-1/CCL2 within tumors that developed in syngeneic C57BL/6 mice after subcutaneous injection of a murine lung adenocarcinoma cell line, TC1." (PMID 33322474, 2020). "Furthermore, macrophage progenitor cells accumulated in the splenic red pulp of a cancer-bearing mouse model with genetically developed lung adenocarcinoma, and macrophages were mobilized in the tumor by tumor-derived factors CCL2 and CSF-1." (PMID 37553633, 2023). "Indeed, lung adenocarcinoma patients with higher levels of CCL2 progress faster and have worse prognosis." (PMID 32528880, 2020). "Finally, we observed a strong correlation between CCL2 and CD11b expression from the human TCGA lung adenocarcinoma dataset." (PMID 32528880, 2020). "These favorable results were recapitulated in a novel mouse model of human lung adenocarcinoma-caused MPE, indicating that CCL2 blockade may modify the disease course of human MPE." (PMID 23967166, 2013). "Here we show that TXA2 mimetic, I-BOP, induced monocyte chemoattractant protein -1(MCP-1)/chemokine (C-C motif) ligand 2 (CCL2) expression at both mRNA and protein levels in human lung adenocarcinoma A549 cells stably over-expressing TP receptor α isoform (A549-TPα)." (PMID 23349788, 2013). "In relation to macrophages, CCL2 has been studied in most detail in mesothelioma with CCL2 concentrations in malignant pleural effusions being substantially higher compared to benign pleural effusions and pleural effusions from patients with lung adenocarcinoma." (PMID 31867277, 2019). "Finally, TRAIL and CCL2 are co-regulated with MDSC/M2 markers in lung adenocarcinoma patients." (PMID 28212753, 2017). "Targeting the C-C Motif Chemokine Ligand 2 (CCL2) and C-C Motif Chemokine Receptor 2 (CCR2) pathways in a lung adenocarcinoma mouse model led to reduced recruitment of M2 macrophages and inhibited tumor growth." (PMID 38545114, 2024).
lung adenocarcinoma (continued). "To examine the effect of hypoxia on CCL2 expression, we performed immunofluorescence staining of HIF‐1Α and CCL2 proteins in noncancerous and cancerous lung adenocarcinoma tissue sections." (PMID 35658112, 2024). "The current study investigated the anti-proliferative, anti-motile and anti-invasive activities of an antagonist against CCR2, CAS 445479-97-0, by blocking the CCL2/CCR2 axis interaction and downregulating MMP-9 protein expression in human lung adenocarcinoma A549 cells in vitro." (PMID 28424406, 2017). "In our hands, a proteasome inhibition regimen designed to target NF-κB activation of lung adenocarcinoma limited MPE formation by suppressing the expression of multiple paracrine mediators of intrapleural adenocarcinoma dissemination and fluid extravasation, including TNF and CCL2." (PMID 20219102, 2010).